SKP1 (S-phase kinase associated protein 1)
Diseases named in the same sentence as SKP1 in open-access papers (continued):
Sharing a sentence is not in itself a finding about the gene and the disease.
tumor (continued). "Skp2 is the F-box protein responsible for substrate recognition in the Skp1-Cullin1-F-box (SCF) E3 ubiquitin ligase and specifically targeting the tumor suppressive proteins such as p27 for ubiquitination and proteasomal degradation." (PMID 24156782, 2013). "FBXL7, an F-box protein that binds to substrates via SKP1-Cullin-1-F-box (SCF) E3 ubiquitin ligase, could enhance polyubiquitylation and degradation of substrates in tumor occurrence and aggression." (PMID 37180696, 2023). "To verify whether CCDC183-AS1 exerted its tumor promoting function through CCDC183-AS1/miR-589-5p/SKP1 axis, we performed rescue experiments using miR-589-5p inhibitor and SKP1 overexpression." (PMID 33541391, 2021). "Of the 143 patient tumours harbouring SKP1 shallow deletions, ~78% (111/143) occur independent of CCNE1 amplification, while ~22% (32/143) co-occur with CCNE1 gene amplification." (PMID 33731859, 2021). "We then quantified the expression of DNER, RBPJ, SKP1, CTNNB1, and CDH2 in solid tumor and paratumor paraffin sections by immunohistochemistry and found strong cytoplasmic positivity of DNER in tumor tissue compared with paratumor tissue, with significant differences (P < 0.05)." (PMID 33329729, 2020). "HULC induced tumor proliferation, migration and cell cycle progression by modulating the expression of Cyclin A/D1/E, p-Rb, c-Myc, CDK2/4, and p16/p21/27, which are targets of Skp-1/2 and inhibitors of CDK2/4 and EZH2." (PMID 26894862, 2016). "From a mechanistic perspective, the modulated functioning of tumor promoter (such as cyclin E, c-Myc, cyclin D1, c-Jun, etc.)or suppressor (e.g. RASSF1) proteins, which are bona fide substrates of SCF assembly, appears to be puppeteer of Skp1 perpetration in either case." (PMID 35789855, 2022). "Thus, the phenotypic differences observed between the two SKP1+/− subclones begin to provide novel insight into how CIN-positive cells may adapt and evolve over long-term growth, and thus provides novel insight into the extensive tumour cell and genomic heterogeneity observed in HGSOC." (PMID 33731859, 2021). "6-OAP treatment did not perturb Skp1 expression, but down-regulated NIPA and Skp2, and up-regulated Cyclin B1 and E-cadherin in tumor samples." (PMID 26474281, 2015).
cancer (43 papers, 2011 to 2025). A tumor composed of atypical neoplastic, often pleomorphic cells that invade other tissues. "Briefly, SKP1 mutations are rare with only 15 missense and 2 truncating mutations (one frameshift and one premature stop codon) identified within six of the 12 cancers assessed." (PMID 35345853, 2022). "In support of this possibility, somatic alterations in SKP1, including mutations, deletions and mRNA misexpression occur frequently in a wide variety of cancer types." (PMID 35345853, 2022). "But, on the other hand, attenuation of Skp1 activity in some cancer cells has been linked to increased genomic instability, replication stress, DNA double-strand breaks (DSB), and neoplastic transformation." (PMID 35789855, 2022). "As an invariable component of the SCF complex, it is apparent that SKP1 is essential for the proper regulation of key substrates involved in many cancer-associated pathways." (PMID 35345853, 2022). "Although the underlying genomic defects accounting for the increases in SKP1 expression observed in this study were not determined, this single example supports the possibility that aberrant SKP1 expression may be a pathogenic driver of cancer." (PMID 35345853, 2022). "In support of reduced SKP1 expression and/or function harboring a potential pathogenic role in oncogenesis, in silico analyses of The Cancer Genome Atlas (TCGA) pan-cancer atlas patient data available through cBioPortal reveal that SKP1 is somatically altered in 12 common solid tumor cancer types." (PMID 35345853, 2022). "Despite the many associations between altered SKP1 expression and cancer, the fundamental impact aberrant SKP1 expression and/or function has on oncogenesis remains unclear." (PMID 35345853, 2022). "Finally, the results of this study may have far-reaching implications beyond HGSOC, as heterozygous loss of SKP1 or CUL1 occurs in at least 12 common cancer types, although this remains to be empirically determined." (PMID 33731859, 2021). "FBXW7 is a component of the SCF (Skp1–Cullin–F-box) E3 ubiquitin ligase complex and can regulate cell proliferation, apoptosis, cell cycle, and differentiation in various human cancers by degrading proto-oncogenes." (PMID 41311387, 2025). "Emerging evidence highlights the role of SCF E3 ligases, consisting of SKP1, cullin‐1, and F‐box proteins, in cancer biology by regulating the ubiquitination and degradation of key proteins." (PMID 41051444, 2025). "SKP1 is the most significant predictive protein for OS and a transcription regulator with significant connections to molecular pathways in cancer and GBM specifically." (PMID 37892181, 2023). "Overall, SKP1 amplifications (two or more additional copies) are rare (0–1.0%), while gains (one additional copy) occur in all 12 cancers analyzed and range from 3.2 to 30.7% in uterine and liver cancers, respectively." (PMID 35345853, 2022). "As an important skeletal protein, the complex formed by SKP1 plays an important role in a variety of malignant tumors." (PMID 33656636, 2022). "Accordingly, genetic studies aimed at identifying SL interactors of SKP1 are highly warranted as the SL interactors are candidate drug targets that when inhibited are predicted to induce the selective killing of cancer cells harboring SKP1 defects." (PMID 35345853, 2022). "On one hand, separate lines of inquiry have documented that Skp1 overactivation or overexpression promotes cancer stemness, cancer initiation, and progression, and correlates with poorer patient outcome as well." (PMID 35789855, 2022). "FBXO6 (F-box protein 6, FBG2) is a substrate recognition component of certain SCF (SKP1, CUL1, and F-box protein)-type E3 ubiquitin ligases involved in the degradation of ER-associated proteins, and its role in cancer is highly complex." (PMID 36147499, 2022).
cancer (continued). "Accordingly, genetic aberrations altering SKP1 expression and/or function will adversely impact the many biological processes normally required to maintain genome stability, and thus aberrant SKP1 expression is predicted to contribute to cancer pathogenesis." (PMID 35345853, 2022). "In this regard, future studies should also assess the clinical utility of SKP1 as a potential prognostic indicator or a novel therapeutic target for cancers." (PMID 35345853, 2022). "To further support a potential role in cancer pathogenesis, we detail the occurrence and frequency of SKP1 alterations within cancer patient samples." (PMID 35345853, 2022). "Indeed, aberrant SKP1 expression and/or function is already associated with several human genetic disorders, including Sjögren’s syndrome (a chronic inflammatory autoimmune disease), sporadic Parkinson’s disease (a neurological degenerative disorder) and cancer." (PMID 35345853, 2022). "Z0933M can be used as a tool molecule for interrogating Skp1 biology and prospective therapeutic avenues in cancer settings." (PMID 35789855, 2022). "While both approaches revealed variable SKP1 expression in both cancer and matched tissues, 56% of cases showed significant increases in expression within tumors relative to control tissues." (PMID 35345853, 2022). "Our findings propose Z0933M as a chemical tool compound to dissect biochemical events of Skp1 functioning in cancer biology, and a potential lead scaffold for the development of new cancer therapeutics." (PMID 35789855, 2022). "We propose Z0933M as valuable tool for future efforts toward probing Skp1 cancer biology, with implications for cancer therapy." (PMID 35789855, 2022). "Next, CNA analyses revealed that each gene is frequently altered in 10 common cancer types, and that SKP1, RBX1, FBXW7 and FBXO5 tend to exhibit more losses, while CUL1 and SKP2 exhibit more gains." (PMID 35008511, 2021). "The E3 ligase SCF-Skp2 conjugated with SKP1 and its accessory protein Cks1 to promote cancer cell proliferation mainly through ubiquitination and degradation of the cyclin-dependent kinase (CDK) inhibitor p27." (PMID 35006464, 2021). "SKP1 is an adaptor component of the SCF E3 ubiquitin ligase complex that exerts an oncogenic function in cancer and that targets regulators of cell cycle progression." (PMID 33670716, 2021). "While genetic alterations or misregulation of the individual F-box proteins are associated with genomic instability and cancer pathogenesis, less is known about the tumorigenic roles of the invariable SCF components SKP1, CUL1, and RBX1." (PMID 34445249, 2021). "Some reports showed that Skp1-Cullin-F-box complex controlled the G1/S phase and led to cancers if became imbalance." (PMID 34384030, 2021). "Note that for all cancer types investigated, samples exhibiting SKP1 copy number losses also tend to correspond with hypermethylated states (i.e., greater β-values) relative to diploid samples or those harboring copy number gains." (PMID 35008511, 2021). "More specifically, the aberrant expression and function of the SCF (SKP1, S-phase Kinase associated Protein 1; CUL1, Cullin 1; F-box protein) complex occurs in an extensive array of cancer types." (PMID 35008511, 2021). "Patient-based data from The Cancer Genome Atlas (TCGA) provides further evidence supporting the possibility that aberrant expression and/or function of the core SCF complex components (SKP1, CUL1, and RBX1) have pathogenic roles in cancer." (PMID 34445249, 2021). "Similar to the CUL7 scaffold proteins, the catalytic components Rbx1 and Skp1 are also regarded as an oncoprotein in most of the cancers." (PMID 33130829, 2020). "F-box proteins, as substrates for S phase kinase-associated protein 1 (SKP1)-cullin 1 (CUL1)-F-box protein (SCF) ubiquitin ligase complexes, mediate the degradation of a large number of regulatory proteins involved in cancer processes." (PMID 32984335, 2020).
cancer (continued). "Skp1 has been suggested to have a role in various cancer forms by contributing to active oncogenic (Skp1)-Cullin1-F-box protein (SCF) complexes." (PMID 31311505, 2019). "Considering the frequency of SKP1 copy number losses in cancer, it remains plausible that a synthetic lethal (SL) paradigm may prove highly effective in a broad range of cancer types." (PMID 35345853, 2022). "Thus, their mouse and human work are consistent with aberrant Skp1/SKP1 function being an early etiological event underlying CIN and possibly contributing cancer pathogenesis." (PMID 35345853, 2022). "This highlights the need to gain better understanding of Skp1 biology in cancer settings." (PMID 35789855, 2022). "Emerging clinical and genetic data now show that aberrant expression and function of the SKP1-CUL1-F-box (SCF; S-Phase Kinase Associated Protein 1 [SKP1] and Cullin 1 [CUL1]) complex induces CIN that may have pathogenic implications in various cancer contexts." (PMID 36496990, 2022). "In addition, Skp1 depletion using genetic methods or Skp1 pharmacological inactivation reduces cancer cell viability or growth." (PMID 35789855, 2022). "Despite this association, the potential pathophysiological impact aberrant SKP1 expression may have in cancer development is only beginning to emerge." (PMID 35345853, 2022). "As the SCF complex is critical for eliciting an effective DNA damage response, perhaps co-treatment with a low-dose SKP1/SCF complex inhibitor would further sensitize cancer cells and synergize with standard chemotherapies to improve response rates and patient outcomes." (PMID 35345853, 2022). "Knockdown experiments have previously suggested that survival of some cancer cell lines (including A549) may depend on Skp1, whereas its pharmacological inhibition with 6-OAP has been demonstrated to reduce the viability of A549 cells." (PMID 35789855, 2022). "SKP1 is a target of anti-cancer therapeutic interventions, but its regulation by phosphorylation remains unknown." (PMID 33670716, 2021). "Additionally, cursory analyses revealed that the core SCF complex member genes typically harbor fewer than 20 mutations within a given cancer type (right), with specific genes, namely SKP1 and RBX1 having fewer than 10 mutations in each cancer type." (PMID 35008511, 2021). "Previous genetic studies have shown that heterozygous knockout of SKP1, CUL1, RBX1 and FBXO7 induces CIN, an enabling hallmark of cancer frequently associated with cellular transformation, drug resistance, metastasis and poor patient prognosis in many cancer types." (PMID 35008511, 2021). "Beyond somatic mutations, SKP1, CUL1, and RBX1 gene copy number alterations including deep deletions (loss of 2 alleles), shallow deletions (loss of 1 allele), gains (gain of 1 allele), and amplifications (gain of ≥2 alleles) are frequently observed in all 12 cancer types." (PMID 34445249, 2021). "Furthermore, as an adaptor protein in SCF complex, SKP1 possesses a broad function in the cells, especially in normal cells; as the result, inhibition of the main downstream pathways, Hippo/YAP signaling, would be a feasible strategy to reduce the side-effect of anti-cancer treatment targeting SKP1." (PMID 33292299, 2020). "Hence, Skp1-targeting represents a promising anti-cancer strategy." (PMID 26474281, 2015). "Thus, defining the underlying molecular etiology giving rise to SKP1 (and SCF complex) dysfunction will be critical to ultimately determine the individual and collective impacts on disease pathology, especially as it potentially relates to cancer development and progression." (PMID 35345853, 2022). "In particular, two studies focused on the impact reduced SKP1 expression has on CIN in colorectal and ovarian cancer contexts." (PMID 35345853, 2022). "SCF complex is mainly comprised of RBX1, SKP1, CUL1 and F-box protein family, whose dysregulation is highly related with cancer progression." (PMID 35006464, 2021).
cancer (continued). "SCF (Skp1-cullin-F-box proteins) E3 ubiquitin ligases are the most well-known members of the ubiquitination–proteasome system (UPS), which promotes cancer initiation and progression." (PMID 34201347, 2021). "As with SKP1, most CUL1 alterations only occur within a given cancer type with the exceptions of E485K (bladder; head and neck; pancreatic; uterine) and Q607H/K (bladder; skin)." (PMID 35008511, 2021). "The top-scoring genes recurring in the four gene sets included key cancer genes, KAT2A, SKP1, FZD1, JAG1 and PSEN2." (PMID 28473661, 2017). "Since SKP-1 mediates ubiquitination and degradation of VPS34 and interacts with MYXV-derived M-T5 protein, VPS34 level and antitumor activity of CAR-T10%MYXV or MYXV are reduced by overexpression of SKP-1 in cancer cells." (PMID 37091978, 2023). "Accordingly, aberrant SKP1 and SCF complex expression and function is expected to disrupt these essential pathways, which may have pathological implications in diseases like cancer." (PMID 35345853, 2022). "Collectively, these data identify SKP1 as a novel CIN gene and further suggest that reduced expression may contribute to cancer pathogenesis." (PMID 35345853, 2022). "To gain novel insight into cancer pathogenesis, we determined the prevalence of genetic and epigenetic alterations in six prototypic SCF complex member genes (SKP1, CUL1, RBX1, SKP2, FBXW7 and FBXO5) from patient datasets extracted from The Cancer Genome Atlas (TCGA)." (PMID 35008511, 2021). "Furthermore, the expression levels of SKP1 in 80 pairs of HCC and adjacent non-cancer tissues were evaluated by Western blot." (PMID 33541391, 2021). "Interestingly, when shallow deletions or gains of SKP1, CUL1, and RBX1 are assessed concurrently within three commonly diagnosed cancers, there is a compounding effect." (PMID 34445249, 2021). "The current study builds upon that model by showing that reduced degradation of Cyclin E1 stemming from a diminished expression of SCF complex components, namely SKP1 and CUL1, is an additional mechanism by which Cyclin E1 levels may increase in cancer cells." (PMID 33731859, 2021). "Cancer cells often undergo Epithelial-Mesenchymal transition (EMT) to acquire the stemness, we next examined whether SKP1 promotes EMT of CRC cells." (PMID 33292299, 2020). "Collectively, these data suggest that while complete loss of SKP1 or CUL1 expression may not be compatible with cell viability (i.e., essential genes), reduced SKP1 or CUL1 expression may have potential roles in cancer initiation." (PMID 33731859, 2021). "However, these relationships are not universal as some cancers do exhibit increases in SKP1 expression relative to control tissues (e.g., chronic lymphocytic leukemia, head and neck, and liver)." (PMID 34445249, 2021). "However, the expression of Skp1 has been detected in a limited number of cancers, and the mechanisms have not been fully elucidated; therefore, further exploration of the role of Skp1 in tumorigenesis and metastasis is needed." (PMID 33130829, 2020). "Finally, our findings may help explain the high prevalence of CIN in a subset of cancers lacking CCNE1 amplification, but in which SKP1, or other SCF complex members are heterozygously or homozygously lost." (PMID 32106628, 2020).
infection (12 papers, 2012 to 2025). The state of being infected such as from the introduction of a foreign agent such as serum, vaccine, antigenic substance or organism. "Similarly, many genes from ETI pathway were up-regulated at different stages of mild and severe infection, for example those encoding suppressor of G2 allele of SKP1 (SGT1), enhanced disease susceptibility 1 protein (EDS1), RPM1-interacting protein 4 (RIN4), or serine/threonine-protein kinase PBS1." (PMID 31671783, 2019). "Western-blotted nuclear and cytoplasmic fractions of uninfected and O. tsutsugamushi infected cells were examined 72 h post infection (hpi) with Cul1, Skp1, and Rbx1 antibodies." (PMID 39976440, 2025). "On the other hand, LV-SKP1A infection led to significant reduced expression of Skp1 protein levels of more than 85%, indicating that the site-directed LV transduction was successful." (PMID 37644186, 2024). "Luciferase assays showed that knockdown of Skp1 expression in host cells resulted in similar levels of NFκB activity upon infection of cells with ΔgogB and complemented strains compared to the wild-type SL1344/pWSK129." (PMID 22761574, 2012). "The roots of erf034, pme17, pub15, and skp1 mutants were less susceptible, especially the erf034 mutant, which had robust lateral roots and many roots without obvious infection." (PMID 36247580, 2022). "On the other hand, the materials that showed less susceptibility in soil culture infection, such as pme17 and skp1, which were not significantly different from Col-0." (PMID 36247580, 2022). "Infection of these transfected cells with ΔgogB complemented with the full-length GogB-2HA showed that FBXO22 was precipitated by GogB-2HA in the absence or presence of Skp1." (PMID 22761574, 2012). "Infection of control shRNA-transfected cells (i.e., those expressing PKR) confirmed the requirement of Skp1 for the growth of WT RVFV, as Skp1 knockdown by siRNA treatment lowered titers by almost 3 orders of magnitude." (PMID 27122577, 2016). "FRP1 interacts with SKP1, a component of the ubiquitin SCF complex that regulate a variety of cellular functions including virulence, and codes for a PR1-like protein constitutively expressed during infection and under a variety of culture conditions." (PMID 28367157, 2017). "Next we examined the effects of knocking down SKP1, CUL1, FBXW11 alone or in combination, in the presence or absence of PKR, on infection levels of RVFV ZH501 in HeLa cells." (PMID 26837067, 2016).